CTSL (cathepsin L)
Diseases named in the same sentence as CTSL in open-access papers (continued):
Sharing a sentence is not in itself a finding about the gene and the disease.
vitiligo (1 paper, 2024). Generalized well circumscribed patches of leukoderma that are generally distributed over symmetric body locations and is due to autoimmune destruction of melanocytes. "The aim of this study was to investigate the possible role of serum granulysin and cathepsin-L in the etiopathogenesis of vitiligo and their association with disease activity and severity." (PMID 38775500, 2024). "There are a very limited number of recent studies on the possible role of granulysin and cathepsin-L in the etiopathogenesis of vitiligo and as indicators of disease severity and activity." (PMID 38775500, 2024). "The mean serum levels of granulysin and cathepsin-L were statistically significantly higher in vitiligo patients compared with the control group (p=0.048 and p=0.024, respectively)." (PMID 38775500, 2024). "A very high positive correlation was found between serum granulysin and cathepsin-L levels in vitiligo patients." (PMID 38775500, 2024). "This study investigates whether granulysin and cathepsin-l could be indicators of cell-mediated cytotoxicity in the pathogenesis of vitiligo and whether their levels measured in the acute phase could be markers that can help predict disease activity and prognosis of vitiligo." (PMID 38775500, 2024). "Although granulysin and cathepsin-L are molecules involved in the pathogenesis of vitiligo, the use of these molecules may not be helpful in assessing disease activity and severity." (PMID 38775500, 2024). "Although granulysin and cathepsin-L are molecules that play a role in the etiopathogenesis of vitiligo, they may not be useful for the assessment of disease severity and activity." (PMID 38775500, 2024).
tumor (151 papers, 2003 to 2026). "Cathepsin L (CTSL) belongs to the papain-like cysteine protease family that is associated with the tumor progression." (PMID 37480054, 2023). "Cathepsin L (CTSL) is a cysteine protease which has been reported linked to tumor occurrence, development, and metastasis." (PMID 36133820, 2022). "CTSL is frequently overexpressed in many cancers, and CTSL expression has been associated with higher histologic tumor grade and metastatic potential." (PMID 33980181, 2021). "Cathepsin L (CTSL) is a cysteine protease that has been reported to be associated with tumor development, recurrence, and metastasis." (PMID 34208465, 2021). "Forced expression of CTSL is associated with increased migration, invasion, and chemotherapy resistance, and inhibition of CTSL activity decreased tumor growth and invasion." (PMID 33980181, 2021). "Our study, however, showed that CTSL also is found in the nucleus of GC; overexpression of nuclear CTSL in tumor tissues was significantly associated with differentiation, local invasion, TNM stage, lymph metastasis, and shorter survival of GC patients." (PMID 32388635, 2020). "Increased CTSL level was found in multiple tumor types and associated with short survival of several cancers." (PMID 25384089, 2014). "Cst6 encodes cystatin M/E, an inhibitor of the cathepsin L cysteine protease, which has been implicated in epidermal differentiation and tumor suppression." (PMID 21949838, 2011). "Cathepsin L, although less well studied than cathepsin B, has been linked to tumor invasion and metastasis." (PMID 17488522, 2007). "Deletion of CTSL rescued KDM4-loss-mediated tumor suppression." (PMID 40457074, 2025). "As a proteinase, the substrates of CTSL include elastin, collagen, and alpha-1 protease inhibitor and thus it is implicated in several pathologic processes, including myofibril necrosis and tumor progression." (PMID 35414771, 2022). "Moreover, loss- and gain-of-function assays demonstrated that CTSL promotes tumor angiogenesis in GC." (PMID 32388635, 2020). "A correlative study was undertaken by performing additional analyses [free fatty acids (FFAs), plasma CTSL, and inflammatory cytokines] on remaining pre-post intervention sera and exploring associations with extant data on tumor Ki67, body composition, physical activity (PA), and fecal microbiota." (PMID 33042834, 2020). "Such a mechanism could also be extended in explaining how the loss of miRNA-200c contributes to tumor progression and which might have greater biological significance if correlated with cathepsin L expression levels." (PMID 33233599, 2020). "We hypothesized that secretion of the proteolytic enzyme cathepsin L by both tumor-associated macrophages and neoplastic cells facilitates tumor cell invasion, a key element of metastasis." (PMID 31565189, 2019). "In addition, injection of an anti-cathepsin L ScFv lentiviral vector into tumors already induced in nude mice inhibited tumor growth and associated angiogenesis." (PMID 31024572, 2019). "Surprisingly, none of the features associated with the early stages of c-Myc-induced tumorigenesis in PNET, such as c-Myc-induced beta-cell proliferation, initiation of tumor angiogenesis, or acute loss of E-cadherin expression, was affected by deficiency in cathepsin L activity." (PMID 25927437, 2015). "Depending on the cell of origin and oncogenic drivers, the loss of cathepsin L in tissue could negatively or positively contribute to tumor cell survival." (PMID 25927437, 2015). "This may explain why inhibition of CTSL in tumor mouse models was associated with increased intestinal and epidermal tumor progression, but decrease of pancreatic tumors." (PMID 23049944, 2012).
tumor (continued). "Thus, high expression of CTSL was also associated with tumor progression." (PMID 30732622, 2019). "However, the tumors that developed in the cathepsin L-deficient background were markedly reduced in size relative to their typical wild-type counterparts, indicative of a role for cathepsin L in enabling expansive tumor growth." (PMID 25927437, 2015). "Instead, its antitumor activity is mediated by extracellular proteases within the tumor microenvironment, particularly cathepsin L (CTSL)." (PMID 41425250, 2025). "We systematically analysed the expression differences of CTSL in tumour and normal tissues using large databases and human tissue samples, confirming significantly higher CTSL expression in tumour tissues compared to normal tissues." (PMID 39893643, 2025). "Our study reveals a novel mechanism in which USP20 competitively interacts with STUB1 to stabilize CTSL and promote tumour progression." (PMID 41261048, 2025). "CTSL is overexpressed in tumour tissues relative to normal tissues and correlates with advanced clinical stages, lymph node metastasis and unfavourable prognosis." (PMID 41261048, 2025). "The effects of CTSL or USP20 depletion on tumour biological behaviour were evaluated through various in vitro and in vivo assays." (PMID 41261048, 2025). "Consistently, IHC scores of both USP20 and CTSL were significantly elevated in metastatic tumours relative to non‐metastatic tumours in the Harbin cohort." (PMID 41261048, 2025). "Cathepsin L has a diverse role in cancer progression, promoting tumor invasion and metastatic activity." (PMID 40621945, 2025). "Deletion of CTSL also eliminated KDM4C-inhibition-induced tumor growth suppression specifically in KDM4C-amplified cell models where CTSL-mediated histone H3 clipping is observed." (PMID 40457074, 2025). "CTSL expression was markedly elevated in tumour samples compared with their matched normal controls." (PMID 41261048, 2025). "The involvement of cathepsin L in numerous physiological processes in vivo, including the regulation of the immune response and tumor dissemination, has been well documented." (PMID 39769543, 2024). "In contrast, reovirus-sensitive tumor cells exhibited significantly higher cathepsin L activity, particularly in the supernatants, with the exception of Mel Mtp cells and other conditionally resistant cell lines." (PMID 39772250, 2024). "CTSL, produced by both tumor cells and macrophages, promotes breast cancer metastasis by driving M0 to M2 differentiation via IL-4." (PMID 39736788, 2024). "Given the importance of CTSL in tumor cell dissemination, there is a pressing demand to develop novel CTSL inhibition strategies." (PMID 38139037, 2023). "In the current work, we analyzed the expression profile of CTSL in different types of tumor tissues and matched normal tissues, in order to predict its potential role as a therapeutic marker." (PMID 35414771, 2022). "Cathepsin L1 and serpin B12 are proteases that are upregulated in many cancers and are correlated to tumor invasion." (PMID 35798767, 2022). "It promotes tumor metastasis mainly by hydrolyzing metastasis-related substrates in the tumor stroma, for example, fibronectin, progelatinase A, cathepsin L, and matrix metalloproteinases (MMPs)." (PMID 35800070, 2022). "Among them, Module2 (highly express RNASE1, C1QA, CD163, CD14, C1QC, FCGRT, and MS4A7) and Module10 (highly express APOC1, CTSB, CTSL, and TYROBP) are more likely to display the characteristics of tumor-associated macrophages (TAMs)." (PMID 35990663, 2022). "The resistant cells showed more pronounced expression of EMT markers, such as ZEB1, Slug, and N-cadherin, and drug-resistant markers, such as MDR1 and cathepsin L, mimicking an advanced tumor signaling circuit." (PMID 36291907, 2022). "The results of tumor xenograft experiment confirmed that CTSL inhibition down-regulated chemoresistance of NB." (PMID 36133820, 2022).
tumor (continued). "It should also be noted that CTSL have tumor-promoting or tumor-suppressing functions in different preclinical models." (PMID 36552871, 2022). "Cathepsin L (CTSL), a lysosomal acid cysteine protease, is found to play a critical role in chemosencitivity and tumor progression." (PMID 36133820, 2022). "Taken together, both genetic in vivo models suggest that CUX1 acts as an important accelerator of tumor development, with p110 CUX1 as cleavage product of oncogenic cathepsin L activity being the most active CUX1 variant." (PMID 34070180, 2021). "As a major cysteine proteinase in lysosome, cathepsin L (CTSL) knockout was found to exacerbate tumor growth in the epidermis of the mice expressing human papillomavirus-derived oncogene K14-HPV16." (PMID 33803301, 2021). "CTSL, while typically expressed in the endosome, has also been shown to be secreted by tumor cells and potentiates invasion in multiple cancer types." (PMID 33980181, 2021). "p110 CUX1 is generated by proteolytical processing of p200 CUX1 via the endopeptidase cathepsin L in several tumor models." (PMID 34070180, 2021). "Cysteine cathepsin L (CTSL1) is an important member of the cathepsin family and contributes to tumor progression through different mechanisms, such as the induction protein degradation and autophagy." (PMID 33933142, 2021). "Proteins with TY-1 domains have been shown to inhibit cathepsin-L (CTSL), a protease implicated in tumor invasion." (PMID 33980181, 2021). "CTSL is secreted by tumor cells and is capable of degrading extracellular matrix proteins and promoting tumor cell invasion." (PMID 33980181, 2021). "As previously discussed, EpCAM and CTSL are both secreted into the extracellular space where they likely come in contact in the tumor microenvironment." (PMID 33980181, 2021). "Multiple proteins with TY-1 domains are known to inhibit cathepsin-L (CTSL), a cysteine protease that promotes tumor cell invasion and metastasis." (PMID 33980181, 2021). "CTSL promotes tumor cell invasion and metastasis by degradation of the interstitial matrix and basement membranes." (PMID 33980181, 2021). "Cancer-associated mutations that prevent EpCAM cell surface expression abrogate the ability of EpCAM to inhibit CTSL activity and tumor cell invasion." (PMID 33980181, 2021). "For instance, cathepsin S type is involved in tumor progression, angiogenesis, tumor growth, similarly, cathepsin L is involved in neovascularization, migration, and invasion processes as well." (PMID 34572798, 2021). "To determine if soluble EpCAM can inhibit CTSL activity, we incubated recombinant EpCAM-Fc with tumor derived SKOV3 cell lysates as a source of CTSL (SKOV3 cells have the highest CTSL activity in the panel of tested cell lines)." (PMID 33980181, 2021). "The result showed that VD in tumor tissue was significantly higher than in non-tumor tissues, and further analysis showed that the nuclear CTSL expression was positively related to the VD of GC tissues." (PMID 32388635, 2020). "We additionally reported gene expression data, finding that Cathepsin L (CTSL) a protease involved in tumor development and metastasis, was upregulated in tumor specimens of men in the weight loss group." (PMID 33042834, 2020). "In the Medaka study, AgNPs significantly downregulated ctsL gene expression levels, which are known as lysosomal cysteine proteinases and are responsible for tumor promotion, bone resorption and growth regulation." (PMID 32325940, 2020). "Overall, the role of CTSL in promoting tumor progression and metastatic aggressiveness have raised significant interest in the upstream genes of CTSL intervention strategies." (PMID 30732622, 2019). "For example, the increased secretion of CtsL via lysosome exocytosis was correlated with enhanced tumor cell migration and invasion." (PMID 31340550, 2019).
tumor (continued). "Our data indicate that cathepsin L inhibition using KGP94 or KGP207 significantly reduces the invasive potential of both tumor cells and macrophages." (PMID 31565189, 2019). "CTSL, the main member of the Cathepsins family, not only takes part in regulating invasion and metastasis of tumor, but also modulates transcription of EMT related genes." (PMID 30732622, 2019). "As was shown, CTSL was high-expressed in most tumor tissues compared with adjacent tissues (P < 0.001)." (PMID 30732622, 2019). "Consistent with previously published results, cathepsin L knockdown in tumor cells reduced tumor cell invasiveness." (PMID 31565189, 2019). "We previously showed that HGSC-secreted cathepsin L (CathL) induces pro-angiogenic changes in disease relevant human omental microvascular endothelial cells (HOMECs), suggesting a role in tumour angiogenesis." (PMID 31269957, 2019). "The upregulation of CTSL in human cancers contributes to tumor growth and survival, and to resistance of PC9 cells to the chemotherapeutic drug gefitinib." (PMID 31370861, 2019). "The mechanism of CTSL mediated tumor resistance is also complex process, and the current results are preliminary." (PMID 31370861, 2019). "Meanwhile, the locations of CTSL and Vimentin in tumor cells were investigated by immunohistochemical staining." (PMID 30732622, 2019). "Simultaneously, our recent study indicated that the expression level of CTSL correlates positively with the degree of tumor malignancy." (PMID 30732622, 2019). "Among total cases of GBC, 77% (31/40) displayed increased expression of CTSL (H-score>4) in tumor cells as compared to only 16% (10/60) of control gallbladder tissues." (PMID 31824841, 2019). "Overall, these studies indicate that cathepsin L from both the neoplastic cell and macrophage populations contribute to tumor cell invasion." (PMID 31565189, 2019). "Our data indicate that cathepsin L supplied from macrophages is important for tumor cell invasion in vitro." (PMID 31565189, 2019). "The increased mRNA expression exhibited a strong positive correlation with enzyme activities of both these proteases in tumor tissues, thereby suggesting the role of increased mRNA levels in elevating the expression of CTSL and CTSB." (PMID 31824841, 2019). "Enzymatic activity of CTSL+B and CTSB exhibited a strong positive association with tumor stage and lymph node involvement in GBC (p < 0.050)." (PMID 31824841, 2019). "CTSL (Ctsll3 in mice), a lysosomal acid cysteine protease, is known to play important roles in tumor metastasis and resistance to chemotherapy." (PMID 29484121, 2018). "The overexpression of Cathepsin L1 is involved in tumor invasion, metastasis and chemotherapy resistance." (PMID 29855483, 2018). "Secretion of cathepsin L by tumour cells leads to a degradation of extracellular matrix components such as collagen, fibronectin and laminin and enables the migration of tumour cells." (PMID 29044689, 2018). "Tumor cells can produce high amounts of cathepsin L, leading to high serum level, which is considered as blood marker of cancer." (PMID 28611951, 2017). "High concentration of cathepsin L in tumor and its vicinity leads to extracellular matrix degradation, higher tumor invasiveness, and several cancer-related health complications." (PMID 28611951, 2017). "We show that deletion of cathepsin L in Myc-driven pancreatic neoplasias results in both a reduction in autolysosomal formation and an increase in tumor cell death." (PMID 25927437, 2015).